MMP16 (matrix metallopeptidase 16)
Diseases named in the same sentence as MMP16 in open-access papers (continued):
Sharing a sentence is not in itself a finding about the gene and the disease.
dupuytren’s disease (1 paper, 2018). "MMP16 expression is decreased in dupuytren’s disease patients, which is a typical fibrosis disease." (PMID 29774121, 2018).
kidney cancer (1 paper, 2024). Primary or metastatic malignant neoplasm involving the kidney. "For instance, earlier studies demonstrated the overexpression of MMP9, MMP12, MMP14, and MMP16 in breast and kidney cancers, emphasizing their role in tumor progression and metastasis." (PMID 39493455, 2024).
lung disease (1 paper, 2008). "MMP16 protein expression was also determined in lung tissue from eight deceased fetuses without lung disease, sampled between 13 and 35 weeks of pregnancy." (PMID 18784838, 2008).
metastasis (1 paper, 2024). The spread or migration of cancer cells from one part of the body (where they first appeared) to another. "MMP16 expression is associated with age, tumor size, histology, clinical stages, lymph node metastasis status, PR status, HER2 status, non-TNBC, and BRCA1 status (P < 0.05), but not with other clinical pathological parameters." (PMID 39267845, 2024).
Mycoplasma infection (1 paper, 2019). "As both gga-miR-146c and MMP16 are highly conserved in multiple species, we propose that there may be a similar strategy for the other species to defend against Mycoplasma infection." (PMID 31137698, 2019).
nasopharyngeal carcinoma (1 paper, 2024). A carcinoma arising from the nasopharyngeal epithelium. "Against this background, we aimed to determine the expression pattern of AKT, IQGAP1 and MMP16, in HPV‐associated cervical and nasopharyngeal cancer tissues." (PMID 39073693, 2024). "MMP16 protein was ubiquitously expressed in cervical and nasopharyngeal cancers as well as non‐cancer tissues." (PMID 39073693, 2024). "Thus, examining the expression patterns of AKT, IQGAP1 and MMP16 mRNA and proteins in HPV‐related cervical and nasopharyngeal cancers will shed more light on HPV‐associated carcinogenesis." (PMID 39073693, 2024). "Current study reports AKT but not IQGAP1 and MMP16 mRNAs differentially expression in cervical and nasopharyngeal cancers, independent of HPV infection status." (PMID 39073693, 2024). "Increased expression of MMP16 in cervical and nasopharyngeal cancers may not have a prognostic value." (PMID 39073693, 2024). "However, the role of MMP16 in cervical and nasopharyngeal cancers has not been well elucidated." (PMID 39073693, 2024).
neuropathy (1 paper, 2024). A disorder affecting the nervous system that manifests with pain, tingling, numbness, and/or muscle weakness. "Given the potential role of MMP-16 in the pathogenesis of neuropathy, it is imperative to further investigate its expression characteristics and mechanisms of action in clinical patients with DN." (PMID 39877847, 2024).
Osteoblastoma (1 paper, 2013). A rare benign bone-forming neoplasm usually arising from the spine. "Indeed, Wnt/beta-catenin target genes involved in bone metabolism, such as BMP2, BMP4, PTGS2 and MMP16, showed high expression levels in osteoblastoma." (PMID 24236197, 2013).
pterygium (1 paper, 2021). A wedge-shaped fibrovascular lesion arising from the bulbar conjunctiva and extending to the cornea. "In this study, multiple types of MMPs (MMP2, MMP3, MMP8, MMP9, MMP11, MMP16, and MMP28) were highly expressed in pterygium." (PMID 33790949, 2021).
renal cell carcinoma (1 paper, 2024). "Transmembrane metalloproteinases MMP-14, MMP-15 and MMP-16 have been found to be significantly expressed in tumor-transformed tissue in renal cell carcinoma and to be present in urine samples from the same patients; however, no reports have been published on their expression in renal cell carcinoma." (PMID 39125675, 2024).
Sepsis (1 paper, 2014). Sepsis is defined as life-threatening organ dysfunction caused by a dysregulated host response to infection. "Susceptibility to sepsis in our study population was related to SNPs in the IL1β, MMP-16, BPI, and DEFβ1 genes." (PMID 25000179, 2014). "Only GG genotype of MMP-16-rs2664349 showed a significant association with an increased risk of developing bacteriologically confirmed sepsis (p = 0.02)." (PMID 25000179, 2014). "Among the patients with bacteriologically confirmed sepsis, only genotype GG of rs2664349 (the MMP-16 gene) showed a significant association with an increased risk (p = 0.02)." (PMID 25000179, 2014). "We found that homozygosis for rs2664349-GG haplotype in the MMP-16 gene is associated with an increased susceptibility to sepsis in general and to microbiological confirmed sepsis in particular." (PMID 25000179, 2014). "However, whereas SNPs in the IL1β and in MMP-16 genes were associated with an increased risk of sepsis, variations of BPI and DEFβ1 seemed to play a protective role." (PMID 25000179, 2014). "This is the first report of the potential effect of a genetic variation in MMP-16 on sepsis, but the finding seems to be consistent with recent evidence that MMPs are not only purely matrix-degrading enzymes as previously thought, but also have multiple immunomodulation mechanisms." (PMID 25000179, 2014).
tendinopathy (1 paper, 2023). "In regard to the expression of metalloprotease-encoding genes, increased expression of MMP2, MMP14, MMP16, ADAMTS2, ADAMTS3 as well as downregulation of MMP10 has also been found in tendinopathy." (PMID 38001919, 2023).
thyroid papillary carcinoma (1 paper, 2023). "Compared with normal tissues, MMP16 expression was up-regulate in thyroid papillary carcinoma." (PMID 36941602, 2023).
tumor (44 papers, 2010 to 2026). "High expression of MMP16 in PCa is associated with tumor staging and tumor cell metastasis, and its membrane localization is functionally required." (PMID 41507135, 2026). "Multivariate analysis demonstrated that MMP16 expression level, T stage, N stage, and tumor grade were independently associated with a decreased OS (P<0.05)." (PMID 27340864, 2016). "In addition, the Pearson correlation coefficient revealed a negative association of circ-0072088 with miR-375 and a positive association of circ-0072088 with MMP-16 in tumor tissues of patients with HCC." (PMID 34568335, 2021). "Similarly, MMP16 expression level, T stage, N stage, and tumor grade were independently associated with a shorter DFS (P<0.05)." (PMID 27340864, 2016). "We found that P2RX7, MMP15 and MMP16 are upregulated in neurosphere cells, indicating a potential role for these genes in tumor formation." (PMID 41400763, 2025). "Functionally, overexpression of HOXA11-AS promoted tumor growth and invasion through regulating miR-146b-5p-MMP16 axis." (PMID 36387262, 2022). "Among genes significantly downregulated by MEG3 knockdown, as determined by a −2 fold-change from MEG3-knockdown to control, were MMP-1, MMP-9, and MMP-16, three metalloproteases with previously characterized roles in tumor metastasis." (PMID 36231143, 2022). "In the clinicopathological analyses, upregulated MMP11, MMP14, MMP16, MMP17, MMP19, and MMP23B were significantly associated with a higher tumor stage." (PMID 34804973, 2021). "The IHC study indicated that there was only weak MMP16 staining in normal liver tissues, while its expression was high in tumor tissues." (PMID 29069779, 2017). "Multivariate analysis demonstrated that high MMP16 expression level, poor tumor grade, and advanced T and N stage were independently associated with both OS and DFS (P < 0.05)." (PMID 28422174, 2017). "In TCGA and GSE39584 database, the log-rank test demonstrated that overall survival (OS) for patients with low MMP16 expression in tumor tissues was significantly higher than those with high expression (P < 0.05)." (PMID 28422174, 2017). "The log-rank test demonstrated that OS for patients with low MMP16 expression in tumor tissue was significantly higher than those in high group (P = 0.018)." (PMID 28422174, 2017). "Transcriptome analysis of mouse fibrotic dermis showed an increase in mRNA levels of regulatory genes, such as Col7a1, Ccn3/Nov, Biglycan, and Matrix Metalloproteinase 16 (Mmp16), a subset of which are also up-regulated in human skin fibrosis and tumor stroma." (PMID 29209359, 2017). "Because high MMP16 expression was statistically correlated with advanced tumor stage in patients’ sample, the impact of MMP16 on GC cells invasion was further investigated." (PMID 27340864, 2016). "The log-rank test demonstrated that there were significantly higher in the cumulative DFS and OS for patients with low MMP16 expression in tumor tissues than those in high group (both P<0.001)." (PMID 27340864, 2016). "Significant differences in GS were identified in relation to the expression profiles of ITGAV1, ITGA3, ITGA6, SPARC, MMP9, and MMP16, markers that were detected in the tumour samples examined." (PMID 26674523, 2015). "Several genes showed progressive increases during tumor growth, including Mmp2, Mmp3, Mmp13 and Mmp16, whereas Timp2 and Mmp27 showed more dynamic fluctuations in expression." (PMID 25848906, 2015). "IHC results revealed that E2F1 was strongly positive in SCLC tumor where MMP-16 was highly expressed, indicating that E2F1 was associated with the expression of MMP-16." (PMID 24755270, 2014). "In the TME, MMP16 promotes tumor cell invasion and metastasis by degrading matrix components." (PMID 40612677, 2025). "Expression of MMP15 and MMP16 may contribute to the neurosphere cells’ ability to establish a tumor when engrafted into mice." (PMID 41400763, 2025).
tumor (continued). "MiR-146b is a known tumor suppressor in many brain malignancies, with targets including tumor necrosis factor receptor (TNFR)-associated factor 6 (TRAF6), matrix metalloproteinase-16 (MMP16) and epidermal growth factor receptor (EGFR)." (PMID 32102476, 2020). "However, we further detected the role of miR-328-3p in the migration and tumor growth of OS cells and found that miR-328-3p regulated the development of OS by downregulating the expression of MMP-16." (PMID 31043859, 2019). "MMP-16 was selected for further study due to its higher expression in SCLC tumor." (PMID 24755270, 2014). "This role for MMPs in tumor pathophysiology also makes them a potential therapeutic target, and high levels of MMP2, MMP9, MMP15, MMP16 have been shown to be expressed in GBM tumor cells and associated with poor prognoses." (PMID 41400763, 2025). "Specially, HCC tumor cell-derived exosome suppressed the metastasis of HCC mediating the degradation of miR-375 via circZFR and upregulated MMP-16." (PMID 36008845, 2022). "Meanwhile, Mmp3, Mmp9, Mmp16 and Mmp10, which belong to the MMP family and are closely related to tumor metastasis, were downregulated." (PMID 35296801, 2022). "The qRT-PCR assay revealed a notable decrease in miR-375 in tumor tissues of patients with HCC and a significant increase in MMP-16." (PMID 34568335, 2021). "MMP11, MMP14, MMP16, MMP17, MMP19, and MMP23b were positively correlated with the tumor stage, that is, the mRNA levels of MMPs in patients with higher tumor stage were always high." (PMID 34804973, 2021). "While the vast majority (86–97%) of microglia showed expression of individual MT-MMPs, we observed significant differences in the proportions of MMP expression in tumor cells: MMP14 was produced by 54%, MMP16 by 80%, and MMP17 by 90% of tumor cells." (PMID 32872536, 2020). "Among the studied genes, the overexpression of the following metalloproteinases in the tumor tissue can be correlated to at least one clinicopathological variable: MMP-1, MMP-2, MMP-9, MMP-11, and MMP-16." (PMID 24737953, 2014). "The fraction of cells that produced MT-MMPs showed differences with regard to the particular MMPs and the location (infiltration zone vs. solid part of the tumor): 51% vs. 54% were positive for MMP14, 65% vs. 74% produced MMP16, and 62% vs. 86% expressed MMP17." (PMID 32872536, 2020). "MT1- and MT2-MMP (MMP15) can each drive tumor cell invasion through basement membranes and the collagen type I-rich interstitial stroma, while MT3-MMP (MMP16) cannot efficiently cleave native collagen type I or confer cells with collagen-invasive ability in vitro or in vivo." (PMID 22164270, 2011). "We could see that about half MMPs are highly expressed in tumor tissues as compared with normal tissues, including MMP9, MMP10, MMP11, MMP12, MMP15, MMP25, MMP26 (all, P<0.05), while some other MMPs decreased in tumor tissues, including MMP2, MMP14, MMP16, MMP24, MMP28(all, P<0.05)." (PMID 32669958, 2020). "Furthermore, in 25 paired HCC tumor tissues and their adjacent normal control, we found MMP16 was significantly upregulated in HCC tissues than their normal control." (PMID 29069779, 2017). "Therefore, our findings showed that MMP16 was a prognostic factor in HCC, ectopic MMP16 expression promoted invasion of HCC cells by inducing EMT process, suggesting a tumor oncogenic function in HCC and provides the potential therapeutic target for the treatment of HCC." (PMID 29069779, 2017).
cancer (39 papers, 2011 to 2026). A tumor composed of atypical neoplastic, often pleomorphic cells that invade other tissues. "The overexpression of MMP16 is associated with poor prognosis and increased risk of metastasis in cancer patients." (PMID 38560573, 2024). "MMP16 gene encodes for the matrix metalloproteinase 16, a protease that degrades the extracellular matrix and promotes cancer cell invasion and metastasis." (PMID 38560573, 2024). "MMP16 encodes matrix metalloproteinase 16, a proteolytic enzyme that plays a role in extracellular matrix degradation during cancer metastasis." (PMID 36601474, 2022). "Further investigation into AGO1, TNRC6B, NOVA1, MMP16, and their connection to miRNA processing could provide deeper insights into the molecular mechanisms underlying cancer recurrence." (PMID 39070144, 2024). "Among the 22 investigated MMPs, seven genes (MMP2, MMP3, MMP10, MMP12, MMP14, MMP15, and MMP16) were upregulated in cancer, while MMP8 was downregulated." (PMID 41728806, 2026). "MMP16 has garnered attention for its involvement in various biological processes, including cancer metastasis, angiogenesis, and immune regulation." (PMID 41150293, 2025). "The MMP9, MMP12, MMP14, and MMP16 genes work synergistically to regulate processes such as tissue remodeling, wound healing, and cancer invasion." (PMID 39493455, 2024). "Matrix metalloproteinase-16 (MMP-16) is a membrane-bound metalloproteinase that is associated with the proliferation, invasion, and migration of cancer cells." (PMID 39273000, 2024). "The prognostic value of high expression levels of MMP9, MMP12, MMP14, and MMP16 in various cancers, as indicated in this study, has also been reported in prior research." (PMID 39493455, 2024). "High expression levels of LincRNA H19, miR-675, MRP3, HOXA1, and MMP16 in cancer tissues correlated with advanced disease stages and poorer survival rates." (PMID 39267845, 2024). "Predominantly, IQGAP1 was highly expressed in both epithelial cancer tissues, whereas MMP16 was ubiquitously expressed in both cancers and normal tissues." (PMID 39073693, 2024). "Inhibition of MMP16 can reduce cancer cell invasion, migration, and metastasis, providing a promising therapeutic strategy for cancer treatment." (PMID 38560573, 2024). "MMP16 has been reported to activate MMP2, an important cancer‐associated MMP involved in the invasion and metastasis of a wide range of carcinomas." (PMID 39073693, 2024). "Protein expression levels of AKT, IQGAP1, and MMP16 in HPV‐infected cancers and controls were determined by immunohistochemistry." (PMID 39073693, 2024). "The results showed that MMP2, MMP9, MMP12, and MMP16 promoter regions in KIRC samples were hypomethylated compared to non-cancer samples." (PMID 38560573, 2024). "In SHH, we identified DMPs in four genes (CDK6, COL25A1, MMP16, PRIM2) that encode proteins which are the target of therapies in clinical trials for other cancers." (PMID 37035203, 2023). "The possible reasons derived are from the anti-oncogene role of miR-328 via multiple pathways (such as PI3K/AKT, MMP16, Notch) in cancers, while some previous studies also show contradictory data that miR-328 acts as an oncogene in some cancers." (PMID 35965521, 2022). "MMP16 is a membrane-type metalloprotease that facilitates cancer progression via multiple mechanisms." (PMID 34730679, 2021). "MMP16 can degrade the components of extracellular matrix and facilitate the migration and invasion of cancer cells." (PMID 34730679, 2021). "Higher levels of MMP16 are detected in cancer tissues compared to normal tissues and they are also associated with poor prognosis." (PMID 32352029, 2020). "MMP-16 induces EMT in HCC, promoting cancer cell invasion and metastases; silencing MMP-16 expression hinders the EMT process by increasing the expression of epithelial cell marker E-cadherin while repressing mesenchymal markers vimentin and N-cadherin." (PMID 31886121, 2019).